LGALS3 (galectin 3)
Diseases named in the same sentence as LGALS3 in open-access papers (continued):
Sharing a sentence is not in itself a finding about the gene and the disease.
tumor (continued). "Galectin-3 enhances metastasis through promoting tumour cell adhesion, invasiveness, and inducing tumour cell proliferation and angiogenesis." (PMID 23285151, 2012). "Recent study from Levy R at al demonstrated galectin-3 mediates cross-talk between K-Ras and Let-7c tumor suppressor miRNA." (PMID 22900040, 2012). "Then, variations in the cellular origin of the tumor would explain the diverse galectin-3 expression patterns in various CCRCC cases." (PMID 21958686, 2011). "Galectin-3 concentrations in normal, intermediate and tumor tissues were examined by immunofluorescence microscopy and on immunoblots with antibodies directed against galectin-3 and renal control proteins." (PMID 21958686, 2011). "Based on these observations, a decline or an increase of galectin-3 during development of a certain tumor cannot be predicted in general." (PMID 21958686, 2011). "We used the immunochemistry method to investigate the expression of galectin-3 and cyclin D1 in the paraffin-embedded tumor tissue of 47 patients (32 men and 15 women; mean age 59.34 ± 8.90)." (PMID 22024187, 2011). "Some of the exosomal proteins particularly galectin-3 and annexins have been shown to be up-regulated in tumor cells, and hence the urgency to define their potential role(s) in the trafficking and utilization of exosomes by tumor cells." (PMID 21915303, 2011). "Taken together, our results suggest that CCRCC tumor formation is characterized by notable synthesis of galectin-3, which is to a significant extent translocated into the cell nucleus." (PMID 21958686, 2011). "Our data revealed a reduction of aquaporin-2, E-cadherin and villin in CCRCC tumor cells from 39 patients concomitant with an increase in galectin-3 in more than two thirds of the cases analyzed." (PMID 21958686, 2011). "In examinated group of 94 patients they showed poorer prognosis for the galectin-1 and galectin-3-expressing tumor in the univariate survival examination and in the multivariate analysis for the galectin-3 positive tumours." (PMID 22024187, 2011). "The cell nuclei were isolated to determine quantities of galectin-3 that were transferred into this compartment in normal or tumor samples." (PMID 21958686, 2011). "Changes in the expression of galectin-3 are heterogeneous and depend on tumor origin as well as on the tissue affected." (PMID 21958686, 2011). "In the first group galectin-3 expression was positive in 5 tumour tissues from 12 (41.6%) and in the second group in 13 from 35 (37.14%)." (PMID 22024187, 2011). "More importantly we demonstrated that the tumor cells that adhered and spread rapidly also expressed high levels of galectin-3, suggesting that this lectin played a role in the rapid adhesion." (PMID 21915303, 2011). "There is striking evidence that galectin-3 plays a role in neoplastic transformation, tumor growth, cancer cell adhesion, metastasis, invasion, and apoptosis." (PMID 21765917, 2011). "Galectin-3 expression was significantly increased in 79% of tumor samples as compared to normal tissues." (PMID 21958686, 2011). "In stage I galectin-3 was positive in 3 from 17 tumor specimen (17.65%), in stage II in 5 from 8 (62.5%), in stage III 7 from 16 (43.75%) and in stage IV in 3 from 6 (50%)." (PMID 22024187, 2011). "On the subcellular level, the balance of cytosolic versus nuclear galectin-3 was shifted towards the nucleus in CCRCC tumor tissues." (PMID 21958686, 2011). "Galectin-3, a lectin, is involved in neoplastic transformation and tumour progression and has demonstrated significant prognostic value, particularly in stages I and II CRC." (PMID 21339979, 2010). "Galectin-3 cleavage is an active process during tumor progression and can be used as a simple, rapid, and reliable surrogate marker for MMPs activity." (PMID 23658855, 2010).
tumor (continued). "A significant correlation of galectin-3 expression was observed with tumor progression in overall cases, and in poorly differentiated adenocarcinoma the expression of galectin-3 in metastatic lymph nodes was stronger than the primary cancer." (PMID 23658855, 2010). "A significant correlation was found between galectin-3 tumor positivity and longer relapse-free and overall survival." (PMID 23658855, 2010). "The TF antigen binding cell surface molecule Galectin-3 is likely involved in the adhesion of metastasizing tumor cells to endothelial cells." (PMID 20433713, 2010). "Lysosome-associated membrane glycoprotein 1 (LAMP1) is a receptor for galectin-3, and was found on the cell surface of highly metastatic tumor cells." (PMID 20831833, 2010). "Other groups also confirm these findings and furthermore show that melanocytes accumulate galectin-3 with tumor progression, particularly in the nucleus." (PMID 23658855, 2010). "Galectin-3, found by SEREX and in the present study by proteome serology, is of great interest as it is one of the very few serologically defined tumor-associated antigens that are present at the outer cell surface." (PMID 19381273, 2009). "A galectin-3 ‘radiation targeted therapy’ delivers the radiation dose specifically to the galectin-3 positive tumor with limited exposure of normal tissues." (PMID 19020658, 2008). "Mice with tumor mass of about 1 gm were injected in the tail vein (i.v.)with 100 μCi of 99mTc-labeled mAb to galectin-3 (30 μg protein/in 100 μl saline solution)." (PMID 19020658, 2008). "Galectin-3 is upregulated in endothelial cells of cancer tissue as found in vivo and in a murine tumor model of hepatocellular carcinoma." (PMID 19055814, 2008). "The Thomsen-Friedenreich antigen (TA) is expressed on human breast and prostate carcinoma cell lines and serves as a ligand for galectin-3 expressed on endothelium, leading to increased tumor cell adhesion." (PMID 19055814, 2008). "As expected the tumor uptake of the galectin-3 specific 99mTc-labelled mAb increased from 3 to 9 hrs post-injection." (PMID 19020658, 2008). "Distinct to C4.4A, which is expressed exclusively by the epithelial tumour cells, galectin-3 can also be expressed by stromal cells and expression becomes upregulated in colitis ulcerosa tissue." (PMID 17912244, 2007). "Galectin-3 was predominantly expressed in the tumour cells, but was also detected in the tumour stroma of some tissue samples." (PMID 17912244, 2007). "Galectin-3 is shown to have dual activity, acting as an anti-tumor protein or aid in tumor progression, dependent on its localization in the nucleus or cytoplasm, respectively." (PMID 19936097, 2007). "Functionally, Galectin-3 depletion restored T cell–mediated tumor control." (PMID 41477833, 2026). "Interestingly, despite its established roles in invasion and metastasis in other tumor models, our data indicate that LGALS3 expression is similar in primary and metastatic PDAC tumors." (PMID 41153387, 2025). "Similarly, bladder tumor tissues exhibit higher galectin-3 expression compared to normal urothelium, further supporting its role in tumor progression." (PMID 40252176, 2025). "Lgals3 and Hmgb1 expression are also highly expressed in the tumour cell population." (PMID 40473819, 2025). "Notably, knockdown of platelet integrin β3, which binds to galectin-3 on tumor cell, significantly abolishes platelet-induced tumor cell proliferation." (PMID 40514754, 2025). "Cells in the dominant subcluster (Neu_0, Neu_1, Neu_2, and Neu_5) with high expression of Ccl3 and Cstb defined as tumor‐specific neutrophils, which were enriched in the NPs group and exert pro‐tumor effects with a similar expression pattern of Cd274, Vegfa, and Lgals3." (PMID 39761175, 2025). "Notably, platelet glycoprotein VI (GPVI) interacts with tumor-derived galectin 3, integrin α6β1 binds to tumor ADAM9, CLEC-2 recognizes tumor podoplanin, and GPIIb/IIIa associates with tumor ανβ3 integrin." (PMID 40723273, 2025).
tumor (continued). "Reciprocally, LGALS3, a marker of human Tregs, may interact with multiple ligands detected on tumor cells, supporting HGSOC progression." (PMID 40164596, 2025). "In addition, the up-regulation of C1qb, C1qa, Lamp1, Lgals3, Gm2a, Gusb, Bax, and other genes helps to enhance the anti-tumor and anti-infection ability of the immune system." (PMID 40767963, 2025). "Galectin-3 has a tumor-promoting effect in different tumors." (PMID 39917614, 2025). "This review systematically elucidates the mechanisms by which galectin-3 interacts with immune cells (e.g., T cells, macrophages) in the tumor microenvironment and evaluates its potential as a therapeutic target, including inhibitor development and combination immunotherapy strategies." (PMID 40935640, 2025). "Indeed, administration of K2 is shown to significantly inhibit galectin-3-mediated tumour growth and metastasis in both chick embryo and mice models." (PMID 41023585, 2025). "More and more evidence has shown that galectin-3 is a multi-functional, multi-mode promoter in cancer development, progression, metastasis and immune suppression in various stages such as in tumour cell adhesion, invasion, angiogenesis and immune evasion." (PMID 41023585, 2025). "Moreover, we show that these EGFR‐high tumour cells overexpressed LGALS3, CD59, laminins (LAMB1 and LAMB3), PROS1 and so on that induced LAG3 and CD44 expression in the associated CD8+ T cells featuring an exhaustion state." (PMID 40621643, 2025). "A key distinction in our study is its focus on the relationship between the EMT and galectin-3; thus, staining was assessed primarily in invasive tumor areas with pronounced tumor budding, while expressions in superficial non-invasive tumor regions were excluded from scoring." (PMID 39451592, 2024). "Thus, in this study, we investigated the impact of Galectin-3 on the interaction between neutrophils, NK cells and tumor cells." (PMID 39759523, 2024). "As expected, HCC tumor demonstrated strong LGALS3 expression." (PMID 38643145, 2024). "Altogether, these studies suggest that Galectin-3 inhibits NK cell mediated tumor killing." (PMID 39759523, 2024). "LGALS3 has been shown to act as a secreted protein that is typically secreted into microenvironment by tumour and binds to the corresponding receptor to promote malignant tumour progression." (PMID 39629136, 2024). "In addition, mRNA analyses showed that non-Vδ1 Vδ2 cells expressed several genes for proteins with tumour-promoting functions, such as neutrophil-recruiting chemokines, Galectin 3, and transforming growth factor-beta induced." (PMID 38953978, 2024). "Next, we wanted to investigate the LGALS3 function in HCC tumor immunity further." (PMID 38643145, 2024). "Interestingly, LGALS3, which is differentially expressed in different cancers, has been shown to exhibit tumor suppressor activity in certain cancer types." (PMID 38643145, 2024). "However, the premetastatic bone microenvironment responds differently to LGALS3 released by different tumor cells." (PMID 39148909, 2024). "Notably, the proportion of neutrophils increased in the metastatic samples, transcriptionally resembling tumor-associated neutrophils (TAN), with a high expression of VEGFA, LGALS3, OLR1, PROK2, MMP9, and IL1RN." (PMID 38358826, 2024). "We thus hypothesized that Galectin-3-induced ROS release in neutrophils may impact NK cell viability and hence their anti-tumor function." (PMID 39759523, 2024). "However, the exact contribution of endothelial galectin-3 to tumor immunomodulation still requires further research." (PMID 38990363, 2024). "Additionally, we observed the predominance of Tumor-Modifying neutrophils, characterized by LGALS3 expression, in the tumor area on sections of GBC-LI." (PMID 38822440, 2024). "We hypothesized that Galectin-3 mediated ROS released from extravasated neutrophils in the metastatic environment of OC ascites would affect NK cell anti-tumor responses." (PMID 39759523, 2024).
tumor (continued). "In conclusion, we report that the high levels of Galectin-3 detected in the tumor microenvironment of HGSC may decrease NK cell eradication of tumor cells in a ROS-dependent manner." (PMID 39759523, 2024). "Consequently, tumor growth in a murine lung tumor model was increased when JAG1 overexpressing tumor cells were used and hampered in galectin-3 knockout mice." (PMID 38990363, 2024). "Using a murine model to study if Galectin-3 induces neutrophil-dependent ROS mediated NK cell death and reduced cytotoxicity towards OC tumor cells in vivo could therefore be of interest for future perspectives." (PMID 39759523, 2024). "Additionally, galectin-3 can disrupt N-cadherin cell–cell junctions, providing a mechanism to promote tumor cell motility and metastasis." (PMID 38927753, 2024). "Thus, similar to galectin-1 and galectin-3, current findings suggests that galectin-8 can stimulate endothelial cell functions but identifying the exact role of the protein in tumor angiogenesis requires further investigation." (PMID 38990363, 2024). "Taken together, the results from this study imply that Galectin-3 may decrease NK cell mediated tumor-killing via neutrophil ROS release." (PMID 39759523, 2024). "We managed to find that while the intraperitoneal injection of 5 μg galectin-3 (Gal3) alone only induced neural activities in the Ve-L/-R of non-tumor-bearing mice, it acted in a cooperative manner with 2 ng LIF to trigger responses of all the signature brain regions." (PMID 38467743, 2024). "Furthermore, our in vitro functional assays with NK cells, neutrophils and tumor cells demonstrated a decreased NK cell response in the presence of Galectin-3." (PMID 39759523, 2024). "Likewise, endothelial galectin-3 expression has also been reported in different tumor tissues, e.g., lung, head and neck, colon, and primary central nervous system lymphomas." (PMID 38990363, 2024). "In OC, Galectin-3 can be detected on the cell surface of primary tumor cells and OC cell lines." (PMID 39759523, 2024). "Interestingly, recent studies suggested that LGALS3 involves in essential cancer-related mechanisms, including cellular metabolism, carcinogenesis, metastasis, neoplasia, angiogenesis, as well as immune escape." (PMID 38643145, 2024). "Ultimately, these results suggest that Galectin-3 may affect NK cell mediated anti-tumor response also at the primary tumor site." (PMID 39759523, 2024). "These engineered exosomes possess evasion capabilities against phagocytosis, attributed to the abundant CD47 proteins from RBC membranes, alongside specialized tumor-homing properties conferred by cancer cell-derived proteins, including EpCAM, Galectin 3, and N Cadherin." (PMID 38542268, 2024). "Taken together, these outcomes indicate that LGALS3 is positively associated with immune cell infiltration and cell chemotaxis and could have a crucial function in HCC tumor immune microenvironment." (PMID 38643145, 2024). "Furthermore, liquid chromatography-mass spectrometry identified that soluble galectin-3 secreted by tumor cells was a potential ligand for TREM2." (PMID 39135069, 2024). "AML-MSCs’ proteome and secretome contained increased abundance of galectin-3 (LGALS3), which can support tumor cell survival and may be involved in AL relapse, and also regulates osteogenic and adipogenic differentiation." (PMID 39769050, 2024). "Therefore, a good understanding of the LGALS3’s regulatory mechanisms, its downstream effectors, and its role in tumor immune microenvironment is of great importance for alone or in combination treatment in HCC." (PMID 38643145, 2024). "Galectin-3 is detected nearly in all the stages of tumor development." (PMID 36873388, 2023). "The tumor microenvironment’s critical component is Galectin 3 (Gal-3)." (PMID 38201234, 2023).
tumor (continued). "We fitted expression of LGALS3 and LGALS3BP against EMT score and arrayed by tumor immune phenotype to find that LGALS3 expression increases alongside the cancer specific EMT signature expression in every tumor immune phenotype and every delineated EMT phase (i.e., EPI, pEMT, and MES)." (PMID 38086828, 2023). "In addition, Galectin-3 exerts a role as a pro-tumor factor by acting within the tumor microenvironment to suppress immune surveillance." (PMID 36936148, 2023). "The cellular localization of the Galectin-3 was shown in benign, adjacent-benign and tumor tissues." (PMID 36936148, 2023). "These measurements imply that galectin-3 is spatially linking all observed phenotypes and thus might play a critical and pleiotropic role in induced anti-tumor immunity in BC." (PMID 36672243, 2023). "Galectin-3 (Gal-3) is a multifunctional protein that plays a crucial role in many physiological and pathological processes, such as cell growth, differentiation, apoptosis, cell adhesion, angiogenesis, inflammation, fibrogenesis, and tumor progression." (PMID 37810435, 2023). "Galectin-3 is also involved in tumor immunity to regulate natural killer (NK) and T cell functions." (PMID 36873388, 2023). "This indicates that galectin-3-mediated protease secretion disrupts tumour cell–cell contacts." (PMID 37055381, 2023). "Binding of extracellular galectin-3 to cell surface glycans on growth factors, death receptors and adhesion molecules promotes cancer cell adhesion, invasion, angiogenesis, and tumour cell escape from immune surveillance." (PMID 37055381, 2023). "Galectin-3 (Gal-3) is a β-galactoside-binding lectin that is highly expressed within the tumor microenvironment of aggressive cancers and has been suggested to predict a poor response to immune checkpoint therapy with the anti-PD-1 monoclonal antibody pembrolizumab." (PMID 37701441, 2023). "Galectin-3 binds to β-galactoside and thus to glycosylated Natural killer (NK) and T-cell surface receptors thereby inducing impairment of NK cell activity and anergy of tumor infiltrating CD8 lymphocytes (CD8 TIL) in cancer." (PMID 38259448, 2023). "Thus, C1GalT1 expression in cancer cells reciprocally controls tumour cell-cell and tumour-macrophage interactions mediated by galectin-3 and MGL with double impact on cancer development and progression." (PMID 37612278, 2023). "In addition, the simpler structures of modified pectins more easily bond to galectin-3 (Gal-3), thus preventing tumor growth." (PMID 36900531, 2023). "The inhibition of MUC1/T antigen—galectin-3 interactions may be a potential strategy to reduce tumor progression and metastasis." (PMID 37345016, 2023). "A lack of association between increased galectin-3 levels and patient age, stage and histological type of tumour was observed, while a positive correlation between the expression of only the cytoplasmic fraction of galectin-3 and a poor prognosis was also observed." (PMID 37238197, 2023). "To determine whether LGALS3 has any association with EMT, we examined its expression across cancer cells arrayed by both tumor immune phenotype and EMT status." (PMID 38086828, 2023). "Other hormones and their receptors, such as ER, and growth factors present in tumor microenvironment may be involved in the regulation of the expression of the Galectin-3." (PMID 36936148, 2023). "This not only provides further support to the action of galectin-3-TF/MUC1 interaction in tumour cell-cell homotypic interactions, it also highlights an important role of cell glycosylation in tumour cell communication with adjacent cells in the tumour microenvironment." (PMID 37612278, 2023). "Finally, in vivo experiments showed that LGALS3 knockdown suppressed tumor growth, with smaller tumor volume and weight compared to the control group, suggesting that LGALS3 functions as a pro-oncogenic regulator in LUAD tumorigenesis and progression." (PMID 37265698, 2023).